TNF (tumor necrosis factor)
Diseases named in the same sentence as TNF in open-access papers (continued):
Sharing a sentence is not in itself a finding about the gene and the disease.
inflammatory skin disease (continued). "Previous reports using genetic models indicated that dysregulation of cell death and TNF signaling in keratinocytes is a potent inducer of inflammatory skin disease." (PMID 33238518, 2020). "In inflammatory skin diseases such as AD, various cytokines, including TNF-α and IFN-γ, and stressors increase the expression of adhesion molecules in keratinocytes and induce leukocyte infiltration into inflamed skin lesions." (PMID 31338033, 2019). "IL-1α and IL-1β, mainly produced by the keratinocytes in the skin, as well as TNF-α are key inflammatory cytokines in inflammatory skin diseases such as dermatomyositis and pemphigus, as well as experimental pemphigoid disease." (PMID 31001258, 2019). "There are some studies that report successful therapy of some inflammatory skin disease with TNF-alpha reducing agents." (PMID 24665368, 2014). "Mice with epidermal specific deletions of IKK2 develop severe inflammatory skin disease in a TNF-dependent manner, suggesting that NFKB signaling is a critical component." (PMID 24465642, 2014). "Rg5 improved inflammatory skin disorders, such as oxazolone-induced chronic dermatitis in mice, by modulating IL-1β and TNF-α production in macrophage cells and IFN-γ from Th cells." (PMID 23698769, 2013). "Additionally, TNF-α stimulates the release of other proinflammatory cytokines such as interleukin-6 (IL-6) and interleukin-8 (IL-8), contributing to inflammatory skin disease." (PMID 40364386, 2025). "Notably, several pathways implicated in inflammatory skin disorders were enriched, including JAK-STAT, AGE-RAGE, TNF, IL-17, and NF-κB pathways." (PMID 40612058, 2025). "Abrogation of TNF signaling results in ameliorated and delayed inflammatory skin disease." (PMID 33238518, 2020). "Moreover, TNF-α has been reported to be part of the inflammatory process of skin inflammatory diseases, and inhibition of TNF-α yields positive effects on the treatment of dermatitis." (PMID 30718736, 2019). "TNF-α is the primary mediator of inflammatory skin disease pathology." (PMID 29679037, 2018). "Moreover, our findings provide further evidence that TNF-induced apoptosis can play a role in inflammatory skin disease and indicate that defects in keratinocytes themselves can initiate TNF-dependent and -independent inflammation." (PMID 26701909, 2015). "In addition, the consistent up-regulation of the TNF signature in each lesional inflammatory skin disease supports the possibility that TNF-neutralizing agents may ameliorate inflammation in all four conditions." (PMID 35486723, 2022). "Thus, modulation of TNF-α activity could be a potent approach for the development of new therapeutic agents in preventing skin aging and inflammatory skin disorders." (PMID 34679744, 2021). "Thus, modulation of TNF-α activity could be a potent approach for the development of new therapeutic agents in preventing skin aging and inflammatory skin diseases." (PMID 34679744, 2021). "HOIL-1 KO mice were born at Mendelian ratios and, in contrast to SHARPIN-deficient mice, failed to develop TNFα-driven inflammatory skin disease and exhibited normal histology of lymphoid organs, liver, lung, and kidney, and the presence of Peyer's patches along the small intestine (not shown)." (PMID 25599590, 2015). "In the context of inflammatory skin diseases, CCL17/TARC and CCL22/MDC production is increased epidermal keratinocytes upon stimulation with TNF-α/IFN-γ, resulting infiltration of immune cells into the lesion area." (PMID 36793948, 2023). "TNF-α and IFN-γ were used to stimulate inflammation in HaCaT cells to represent inflammatory skin diseases in an in vitro model." (PMID 36615751, 2022). "TNF-α/IFN-γ was used to induce inflammation in HaCaT cells, which is representative of inflammatory skin disease in an in vitro model." (PMID 36077254, 2022).
inflammatory skin disease (continued). "The ability of TNF-α/IFN-γ to synergistically induce production of cytokines and chemokines by keratinocytes has been exploited in an inflammatory skin disease." (PMID 29932162, 2018). "Therefore, the TNF-α/IFN-γ-stimulated HaCaT cell model serves as a pertinent and efficient system to study the potential therapeutic impact of kahweol on inflammatory skin diseases, especially AD." (PMID 38666948, 2024). "ML analysis elucidated seven features in common among the 15 most important features for classifying each inflammatory skin disease from control, including the IGS and the TNF, IL-23 complex, plasma cell, IL-12 complex, anti-inflammation, and T cell IL-23 signatures." (PMID 35486723, 2022). "AS inhibits the production of NO in a concentration-dependent manner and inhibits inflammatory cytokines (IL-6, TNF-α) in LPS-stimulated mouse macrophage RAW264.7 cells, suggesting that AS has potential for the treatment and prevention of inflammatory skin diseases." (PMID 36616208, 2022). "Thus, treatment of TNF-α and IFN-γ has been regarded as a common in vitro model for inflammatory skin disorders." (PMID 33802009, 2021). "Therefore, by elucidating the effects of Chinese herbal medicines on the cellular signalling pathways induced by TNF-α, we could reduce the effects of these inflammatory molecules, and identify the potential and feasibility of Chinese herbal medicines for the treatment of inflammatory skin diseases." (PMID 32076123, 2020). "With this new genetic mouse model, we can confirm that the inflammatory skin disease that results from the epidermal deletion of cFLIP is strongly but not exclusively dependent on TNF." (PMID 33238518, 2020). "Epidermal keratinocytes release various inflammatory mediators, such as chemokines and adhesion molecules by tumor necrosis factor (TNF)-α and interferon (IFN)-γ stimulations; these factors are involved in the development of inflammatory skin diseases, including AD." (PMID 26104582, 2015). "TNF-α stimulation led to a significant upregulation of MMP-9 secretion, which was markedly reduced following treatment with Withaferin A-loaded liposomal gel, further emphasising the potential of Withaferin A formulations to modulate tissue remodelling in inflammatory skin disorders." (PMID 41404493, 2025). "Inflammatory factors, such as IL-1α, IL-1β, IL-6, and TNF-α, are upregulated in keloid tissues, suggesting that keloids may be considered inflammatory skin disorders, specifically of the reticular dermis, rather than tumors." (PMID 39119435, 2024). "When the epidermal barrier of the skin is damaged by physical or chemical stimuli, many cytokines (IL-1β, IL-6, TNF-α, IL-5, and TSLP) and chemokines (MCP-1, RNATES, TARC, MDC, CXCL8, and CXCL10) are expressed in stimulated keratinocytes to promote the progression of inflammatory skin diseases." (PMID 36670888, 2022). "It has been shown to promote a pro-inflammatory response by priming keratinocytes, macrophages or inflammatory dendritic epidermal cells (IDEC) for TNFα, CXCL10 and IL-23 production respectively, and therefore may contribute to the elicitation of inflammatory skin diseases." (PMID 22761702, 2012). "Of further importance, these actions of DMG-Na were observed in all three in vitro keratinocyte systems, modeling a wide array of inflammatory skin diseases, irrespective of whether the inflammation was induced by TLR3 stimulation, the combination of INFγ and TNFα, or UVB irradiation." (PMID 37511024, 2023).
diabetic neuropathy (72 papers, 2003 to 2026). A chronic, pathological complication associated with diabetes mellitus, where nerve damages are incurred due to diabetic microvascular injury involving small blood vessels that supply these nerves, resulting in peripheral and/or autonomic nerve dysfunction. "TNF-α is a pro-inflammatory cytokine implicated in the development and progression of diabetic neuropathy." (PMID 40149566, 2025). "The findings underline the potential function of TNF-α as a biomarker and contributor to diabetic neuropathy." (PMID 38179375, 2023). "The over-expression of pro-inflammatory cytokines such as TNF-α, IL-2 receptor, IL-1, and C-peptide in diabetic neuropathy suggests that inflammation is associated with diabetic neuropathy." (PMID 32591628, 2020). "Inflammatory cytokines (including, but not limited to, IL-8 and TNF-α) have been shown to be associated with the progression of diabetic neuropathy." (PMID 32764756, 2020). "Patients with painful diabetic neuropathy were found to have increased mRNA and blood protein levels of IL-1β, IL-2, TNF-α, CRP, and LEP, which could be associated with neuronal dysfunction." (PMID 39408723, 2024). "This underlines the potential of TNF-α as a biomarker and contributor to diabetic neuropathy." (PMID 38179375, 2023). "Moreover, the association between diabetic neuropathy and tumor necrosis factor-alpha has been suggested to be stronger than the association between C-reactive protein and diabetic neuropathy." (PMID 37762893, 2023). "Furthermore, elevated hs-CRP, IL-6, TNF-α, IL-1 receptor antagonist, and soluble intercellular adhesion molecules have been associated with incident diabetic neuropathy." (PMID 35329958, 2022). "This constituent of EOCz inhibited early and late cellular responses transduced by the proinflammatory cytokine TNF-α, a molecule strongly associated with the genesis of diabetic neuropathy, and showed anti-edematogenic activity at relatively low doses (10 mg/kg)." (PMID 33925228, 2021). "This may underlie the pronociceptive effects of TNF-α and suggests a molecular mechanism responsible for pain hypersensitivity in diabetic neuropathy patients." (PMID 31888677, 2019). "For instance, studies have shown that TNF-α can induce COX-2 expression, which is implicated in the pro-inflammatory response seen in diabetic neuropathy." (PMID 40149566, 2025). "Inflammatory markers, including TNF-α, IL-6, and high-sensitivity CRP, show elevated levels in diabetic neuropathy but typically achieve lower diagnostic performance (AUC 0.65-0.75) compared to our NSE results (AUC 0.863)." (PMID 40755599, 2025). "The ethanolic extract of G. sylvestre reduced the levels of TNF-α, IL-1β, and IL-6 in rats with diabetic neuropathy." (PMID 40006756, 2025). "Cachectin, also known as tumor necrosis factor-alpha (TNF-α), is a pro-inflammatory cytokine critical in developing diabetic neuropathy." (PMID 40149566, 2025). "Serum levels of TNF-α, IL-1β, and IL-6 are considerably greater in diabetic neuropathy patients than in healthy people, according to clinical research." (PMID 40149566, 2025). "Elevated levels of TNF-α have been observed in patients with diabetic neuropathy, correlating with reduced nerve conduction velocities and increased pain symptoms." (PMID 40149566, 2025). "Pro-inflammatory cytokines, including TNF-α, IL-1β, and IL-6, are critical drivers in the development of diabetic neuropathy, but chemokines and anti-inflammatory cytokines also play a substantial role in modulating the disease." (PMID 40149566, 2025). "Our recent findings indicate that ALA supplementation enhances endothelial function, as reflected by changes in the serum levels of ADMA and TNF-α in patients with diabetic neuropathy." (PMID 39769041, 2024). "TNF-α blockers have been found to reduce allodynia in diabetic mice, indicating their potential use in treating diabetic neuropathy." (PMID 39595909, 2024).
diabetic neuropathy (continued). "Research into various substances and treatments for painful diabetic neuropathy has revealed multiple promising approaches, including anti-inflammatory agents, TNF-α inhibitors, antioxidants, and novel therapies." (PMID 39408723, 2024). "Elevated levels of CRP, interleukin (IL)-1, IL-6, C-X-C motif chemokine ligand 10 (CXCL10), tumor necrosis factor (TNF)-α, IL-12 (p70), IL-13, and IL-17A are associated with an increased risk of T2DM and diabetic neuropathy." (PMID 39408723, 2024). "Reduced levels of pro-inflammatory cytokines such as TNF-α and IL-6 following gut microbiota intervention have also been shown to correlate with improved symptoms of diabetic neuropathy, including reduced pain and improved peripheral nerve function." (PMID 39727989, 2024). "Ongoing and more extensive clinical trials with the aim of investigating anti-inflammatory agents, TNF-α inhibitors, and antioxidants are needed to advance deeper into the understanding and treatment of painful diabetic neuropathy." (PMID 39408723, 2024). "Apart from the pathophysiological role of cytokines, one study provided diagnostic information using serum levels of IL-6, IL-17, and TNF in patients with diabetic neuropathy." (PMID 36604634, 2023). "The biomarker studies (SOD, NO, LPO, Na+K+ATPase, and TNF-α) further confirmed thymol's diabetic neuropathy protective action." (PMID 35528161, 2022). "Thymol aced the significant reduction of diabetic neuropathy pain by involving various mechanisms which lead to restoration of levels of Na+K+ATPase, inhibition of the elevated cytokines, reduction of TNF-α, and decrease in the NO levels." (PMID 35528161, 2022). "There was a significant increase in the TNF-α gene expression in the posterior section of the diabetic neuropathy group compared to the healthy control group (P < 0.05)." (PMID 35655729, 2022). "Vitamin B12 deficiency and diabetic neuropathy are very high among metformin-treated T2DM patients and it is associated with increased GPA, IFA, TNF-α and cardiometabolic risk factors (higher LDL and TC and lower HDL)." (PMID 33784336, 2021). "Another group has also reported elevated levels of TNF-α in the serum samples of patients with diabetic neuropathy." (PMID 33669048, 2021). "Vitamin B12 deficiency and diabetic neuropathy are very high among metformin-treated T2DM patients and it is associated with increased GPA, IFA and TNF-α." (PMID 33784336, 2021). "It reduces the expression of IL-1β and TNF-α, thereby inhibiting the neuroimmune activation of microglia and alleviating the progression of diabetic neuropathy." (PMID 34159207, 2021). "An experiment conducted to detect TNF-α involvement in diabetic neuropathy reported diabetic TNF-α (-/-) mice were protected from sensory nerve conduction velocity and motor nerve conduction velocity compared to control mice." (PMID 34868777, 2021). "Another work, on the other hand, showed Notch1 signaling promoted TNF-α production in neurons of diabetic neuropathic rats, as an essential mechanism in diabetic neuropathy." (PMID 34646085, 2021). "Diabetic patients with increased TNF-α, inducible nitric oxide synthase levels have more probability to develop diabetic neuropathy." (PMID 34868777, 2021). "The existing relationship between the presence of diabetic neuropathy and proinflammatory cytokines, e.g., TNF-α, has been extensively studied." (PMID 32908447, 2020). "Ortmann and Chattopadhyay highlighted the importance of TNF-α as an additional pathogen in the development of diabetic neuropathy." (PMID 31888677, 2019). "On the other hand, upregulation of inflammatory mediators of COX-2, iNOS, and TNF-α reported in the course of diabetic neuropathy, blocking of these mediators lead to a marked reduction in pain intensity." (PMID 28969623, 2017).
diabetic neuropathy (continued). "Recent evidence shows that treatment with resveratrol, a polyphenolic compound enriched in grapes and red wine, ameliorates elevated levels of tumor necrosis factor (TNF)-α, interleukin (IL)-6, and cyclooxygenase-2 in experimental diabetic neuropathy." (PMID 22973402, 2012). "The pairing of sildenafil and metformin may effectively reduce pain sensitivity in diabetic neuropathy patients by decreasing the activity of iNOS, which is elevated due to elevated levels of inflammatory cytokines like TNF-α and IL-6." (PMID 40149566, 2025). "Administering fish oil attenuated the pain in diabetic rats and was followed by a decrease in TNF-α levels, suggesting that reducing this inflammatory cytokine could ameliorate painful diabetic neuropathy." (PMID 39408723, 2024). "Additionally, they improve nerve function and alleviate inflammation by suppressing markers like TNF-α and IL-6, underscoring their promise in therapeutic applications for diabetic neuropathy." (PMID 39727989, 2024). "In addition, a recent study demonstrated that inflammatory cytokines, particularly tumour necrosis factor (TNF)‐α, are important predictors of diabetic neuropathy over a period of 5 years." (PMID 36757903, 2023). "There is growing evidence that elevated TNF-α concentrations enhance sodium absorption, resulting in renal hypertrophy and salt retention, which are characteristic abnormalities during the early stages of diabetic neuropathy." (PMID 36636607, 2023). "This may be due to AGE-RAGE interaction which occurs in hyperglycaemic conditions, consequently releasing TNF-α and inducing neuroinflmmation and oxidative stress in diabetic neuropathy." (PMID 34012975, 2021). "TNF-α is a potent pro-inflammatory factor in diabetic neuropathy." (PMID 31894843, 2020). "In addition, we previously reported that TNF-α was involved in the pathogenesis of diabetic neuropathy in mice and that inactivation or inhibition of TNF-α ameliorated diabetic neuropathy and reduced hyperalgesia." (PMID 24642694, 2014). "It is not evidently clear if diabetic neuropathy is a demyelination or axonal disease, or subsetted into either, and therefore the treatment of diabetic neuropathy using anti-TNFα may potentially cause damage." (PMID 37483613, 2023). "Preclinical studies showed that in diabetic animals there is an increase in TNF-α concentration in serum, and this in turn induces an increase in the expression of the sodium channel NaV1.7, which results in the sensitization of nerve endings and implicitly the development of diabetic neuropathy." (PMID 37629665, 2023). "GLP-1RAs such as liraglutide and exenatide decrease pro-inflammatory cytokines, tumor necrosis factor-alpha (TNF-α), and interleukin-1β (IL-18) in rodent mouse models of diabetic neuropathy." (PMID 40427515, 2025). "Andaliman extract potentially serves as a therapy for diabetic neuropathy in T2DM by lowering BGL and inhibiting the expression of TNF-α and TRPA-1." (PMID 39101085, 2024). "Till today, no clinical trials have addressed the effect of NAC on TNF levels in diabetic neuropathy." (PMID 40038825, 2025). "In terms of neuropathic pain, systemic administration of GAS relieved hyperalgesia and allodynia in models of painful diabetic neuropathy and chemotherapy-induced neuropathic pain via inhibition of DRG neuron hyperexcitability, inhibition of microglial activation, or reduction of TNF-α and IL-1β." (PMID 38835032, 2024). "It is therefore recommended that those with an underlying demyelinating disease (potentially such as those with a diabetic neuropathy) do not take anti-TNFα therapy." (PMID 37483613, 2023). "Endurance training reduced the sensitivity of the nervous system to thermal hyperalgesia and mechanical allodynia; also, compared to the diabetic neuropathy group, the gene expressions of NLTP3, P38 MAPK, TNF-α, and IL-1β were significantly reduced by endurance training (P < 0.05)." (PMID 35655729, 2022).